IL19 (interleukin 19)
Diseases named in the same sentence as IL19 in open-access papers (continued):
Sharing a sentence is not in itself a finding about the gene and the disease.
psoriasis (continued). "Therefore, IL-19 is recognized as an important player in the pathogenesis of systemic inflammatory diseases such as psoriasis, asthma, rheumatoid arthritis, and sepsis." (PMID 25794104, 2015). "In light of that, a natural compound like RSV, which might increase the RXR gene expression and decrease IL-17A, IL-17F and IL-19 gene expression in psoriasis-affected skin, could be an interesting new treatment modality in human clinical trials." (PMID 25965695, 2015). "Although IL-19 has been shown to be increased in both Th1- and Th2-dominant diseases such as psoriasis and asthma, respectively, data from IL-19 deficient mice and human data autoimmune diseases and other inflammatory conditions suggest that IL-19 has a potent anti-inflammatory activity." (PMID 24699268, 2014). "IL-19 is involved in many diseases, for example, psoriasis, asthma, and endotoxic shock." (PMID 23468852, 2013). "IL-19 acts as a proinflammatory factor in psoriasis, asthma, sepsis, and RA." (PMID 23468852, 2013). "IL-19, like IL-20, has been shown to be produced under inflammatory conditions and is thought to play an important role in the pathogenesis of some inflammatory diseases, such as psoriasis." (PMID 23303806, 2013). "A causal role for IL-19 in psoriasis has not been well established, though the data support a stronger implication for the IL-19 family member IL-20 in this disease." (PMID 22844641, 2012). "It has been reported that the cytokines IL-19, IL-20 and IL-24 are highly expressed in the inflammatory sites of psoriasis, and may thus mediate the progression of psoriasis." (PMID 22792286, 2012). "IL-19 could amplify IL-17A effects on keratinocytes in psoriasis." (PMID 33681365, 2021). "Additionally, it has been suggested IL-19 might act as an assessment tool for psoriasis and atopic dermatitis patients, and along with IL-23/IL-17, has strengthened its role as a biomarker for chronic inflammatory disorders." (PMID 34925353, 2021). "In addition to keratinocytes, dermal fibroblasts, through interaction with immune cells and cytokines such as IL-17A and TNF in psoriasis, can be a major source of IL-19 and IL-24 that contribute to perpetuation of psoriatic symptoms such as keratinocyte proliferation and acanthosis." (PMID 34616394, 2021). "Importantly, our research shows that the IL-19 results obtained in psoriasis are replicable in atopic dermatitis, a common and relapsing inflammatory skin disease (with less defined skin lesions than psoriatic plaques) affecting a wide range of age groups with high global prevalence." (PMID 30914699, 2019). "Resveratrol ameliorates psoriasis, and changes expression of retinoic acid stimulated genes, IL-17 signalling pathways, IL-17A and IL-19 mRNA levels in a beneficial manner, which suggests resveratrol, might have a role in the treatment of psoriasis and should be explored further in a human setting." (PMID 25965695, 2015). "IL36G was also highly expressed in psoriasis, and correlation analysis indicated that IL36G was closely related to IL36A, IL19, CXCL1, and CXCL8, all of which participate in the pathogenesis of psoriasis." (PMID 40159643, 2025). "Regarding its function in psoriasis, STAT3 activation in psoriatic keratinocytes occurs by IL-17, IL-19, IL-21, IL-22, visfatin, and IL-36." (PMID 34679602, 2021). "In psoriasis patients treated with the JAK1/2 inhibitor baricitinib or the TNFα antagonist etanercept, IL-19 levels were also highly correlated with PASI scores, and decreases correlated with PASI improvement." (PMID 30914699, 2019). "Similar to what was observed in psoriasis, PASI 100 improvements at 12 weeks were correlated with reduction of circulating IL-19 to normal levels at 4 weeks (one-way ANOVA p < 0.0001), with the majority of the poor PASI responders being in the placebo group." (PMID 30914699, 2019). "Decrease in the gene expression of IL-19, IL-17A, and IL-23 levels further confirms the potent effect of SEL001 on IMQ-induced psoriasis." (PMID 29867905, 2018).
psoriasis (continued). "TWEAK alone cannot promote full AD or psoriasis phenotypes but it can promote chemokines common to both AD and psoriasis from keratinocytes and fibroblasts, as well as characteristic cytokines of both diseases such as TSLP and IL-19." (PMID 28530223, 2017). "Like IL19, the expression of the IL20 gene is also increased in inflammatory skin diseases like AD or psoriasis and IL20 mRNA is upregulated in lesional compared to non-lesional psoriatic skin." (PMID 23531535, 2013). "Baseline IL-19 levels in patients with psoriatic arthritis were increased compared to normal, although not to the level seen in patients with moderate-to-severe psoriasis." (PMID 30914699, 2019). "In addition to chemokines, we found that TWEAK activity was required in vivo for the production of two other mediators of atopic dermatitits or psoriasis, TSLP and IL-19, respectively." (PMID 28530223, 2017). "Data from mice suggests that this elevation can augment epidermal hyperplasia, since overexpression of either IL-20 or IL-24 (but not IL-19) elicits a psoriasis-like phenotype." (PMID 23915137, 2013). "Apart from significant genetic association of Hepatitis C virus clearance with IL10/19 and IL20, and psoriasis with IL19/20 and IL24, to our knowledge no additional disease association studies with these cytokine genes have been conducted." (PMID 16959027, 2006). "A mouse model of imiquimod-induced psoriasis showed that RSV can ameliorate psoriasis-induced damage by reducing the thickness of the skin and downregulating the mRNA expression levels of IL17 and IL19, which are key cytokines in the development of the disease." (PMID 37445960, 2023). "Our finding that TWEAK can promote the expression of both TSLP and IL-19 from keratinocytes or dermal fibroblasts provides a further mechanism by which TWEAK can contribute to the development and/or maintenance of the clinical phenotypes of both AD and psoriasis." (PMID 28530223, 2017). "However, whether other resident cells, such as skin fibroblasts, are a source of IL-19 and whether in situ IL-19 expression is normalized in patients with psoriasis treated with anti-IL-17 therapy is not clear." (PMID 34616394, 2021). "One can observe that the top psoriasis genes, including IFNg genes OASL, MX1; IL17-regulated CCL20 and IL19 are not different in the PPPP/PPP as compared with normal acral skin." (PMID 27152848, 2016). "Most well known psoriasis related genes activated in non-lesional skin are IL6, IL22, IL36A, IL36G, IL19, IL20, S100A7 and S100A12." (PMID 25897967, 2015). "This indicates that IL-19 and IL-24, rather than IL-22, IL-17A or IL-17F, were responsible for the late stage (day 10) keratinocyte hyper-proliferation and acanthosis in the IMQ-induced psoriasis mouse model during anti-IL-10 treatment." (PMID 34616394, 2021).
asthma (21 papers, 2008 to 2024). "IL-19 has been implicated in the pathogenesis of human asthma by increased levels of this cytokine in the serum of patients." (PMID 22110701, 2011). "In respiratory diseases, IL-19, which is reported involved in inflammatory responses and causing pulmonary injury by activating lung epithelial cells, is positively associated with the progression of asthma and chronic obstructive pulmonary disease (COPD)." (PMID 35281428, 2022). "Therefore, both the suggested evolutionary pressure by parasites on the human il19, IL20RB and IL20RA genes and the association of IL-19 with asthma imply a critical role of IL-19 for the control of Th2 responses." (PMID 22110701, 2011). "IL-17 treatment induces IL-19 expression, and the levels of IL-13 and -19 are closely related to the Th2 response to human asthma." (PMID 38956273, 2024). "The expression of IL-19 is reported increased in asthma and COPD patients, and shows the positive correlation with the progression of these diseases." (PMID 35281428, 2022). "We also treated bronchial fibroblasts of severe asthma with IL-19 and assessed their ACE2 and TMPRSS2 expression." (PMID 35111161, 2021). "While IL-19 cytokine was mostly associated with increased ACE2 receptor in airway epithelium and sputum samples of asthma cohorts." (PMID 35111161, 2021). "In summary, this is the first report demonstrating that inhibition of IL-19 signaling by targeting IL-19 or IL-20R1 protected mice and rats from developing asthma in the rodent models." (PMID 31114590, 2019). "Results from IL-20R1−/− mice suggested that IL-19 signaling through IL-20R1 contributed to Der p-induced asthma." (PMID 31114590, 2019). "We previously showed that IL-19 induces T-helper 2 (Th2) cytokines and that asthma patients had higher serum IL-19 levels." (PMID 31114590, 2019). "We previously reported higher IL-19 expression in asthma patients and that patients with high IL-19 expression also have high IL-4 and IL-13 expression." (PMID 31114590, 2019). "The Der p-induced asthma model was associated with increased AHR and bronchial wall thickening, elevated serum IL-19, IL-13, IgE levels, BALF IgA levels, increased immune cell infiltration, and tissue IL-33 and CCL11 in the lungs." (PMID 31114590, 2019). "This possibility is supported by the increased levels to IL-19 levels found in asthma and uremia, two Th2 behavior diseases." (PMID 24718601, 2014). "IL-17 treatment induces IL-19 expression, and the IL-13 and -19 levels are closely correlated with the Th2 response in human asthma." (PMID 23710200, 2013). "IL-19 contributes to a range of diseases and disorders, such as breast cancer, asthma, endotoxic shock, uremia, psoriasis, rheumatoid arthritis, and periodontal and vascular disease." (PMID 23710200, 2013). "High IL-19 levels were observed in patients with asthma and also in an allergen-inducible asthma animal model." (PMID 23855879, 2013). "Serum IL-19 levels are increased in children with asthma when compared with normal children, and airway epithelial cells of asthma patients exhibit increased IL-19 expression." (PMID 22844641, 2012). "As expected, given the Th2 nature of the disease, IL-19 has a demonstrable, though yet unclear, role in the development of asthma." (PMID 22844641, 2012). "IL-19 expression in airway cells can be modulated by adenosine receptors, which play a role in asthma-related cell signaling." (PMID 22844641, 2012). "Interleukin (IL)-19 has been reported to enhance chronic inflammatory diseases such as asthma but the in vivo mechanism is incompletely understood." (PMID 22110701, 2011). "IL-19 is thought to be significant for human health because increased IL-19 levels have been reported in asthma." (PMID 22110701, 2011). "Moreover, we confirmed that anti-IL-19 mAb (1BB1) attenuated lung inflammation in a rat ovalbumin-induced asthma model." (PMID 31114590, 2019).
asthma (continued). "Our results demonstrated that targeting IL-19 or IL-20R1 could ameliorate Der p-induced asthma in the mouse model." (PMID 31114590, 2019). "However, little is known about the molecular mechanism of IL-19 signaling in the pathogenesis of asthma." (PMID 31114590, 2019). "IL-19 is elevated in asthma patients and in uremic patients." (PMID 24718601, 2014). "IL-19 has been demonstrated to increase Th2 cytokine expression in activated T cells and activated monocytes and its expression has been shown to be increased in certain Th2-mediated diseases such as atopic dermatitis and asthma." (PMID 24699268, 2014). "IL-19 levels increase in acute systemic inflammatory status, for example, in cardiac surgery patients using a cardiopulmonary bypass; IL-19 is also involved in the pathogenesis of mouse models of septic shock and asthma." (PMID 23468852, 2013). "While the role of IL-19 in determining the expression of Notch receptors in B cells remains to be determined, our data strengthen the notion that one of the biological roles of IL-19 is to regulate the stimulation of B cells and B cell responses in asthma." (PMID 22110701, 2011). "The serum level of IL-19 in patients with stable asthma is increase compared with healthy controls." (PMID 18315837, 2008). "IL-24 shares two heterodimeric receptors (IL-20R1 and IL-20R2) with IL-19 and IL-20, and whether these receptors have similar or redundant biological effects on airway remodeling in airway epithelial cells or asthma models remains unclear and needs further examination." (PMID 36100847, 2022). "IL-19 might play an important role in the pathogenesis of asthma." (PMID 32886659, 2020). "Thus, IL-19 inhibitors might be novel and potent therapeutics for asthma because IL-19 likely mediates early allergic response after allergen exposure and attribute to the development of Th2-dominant airway inflammation." (PMID 31114590, 2019). "Thus, we tested whether IL-19 specific mAb 1BB1 would attenuate pulmonary inflammation in the OVA-induced asthma model in rats." (PMID 31114590, 2019). "Bronchial epithelial cells from asthma and COPD patients express large amounts of IL-19, which is involved in allergic airway inflammation through the activation of group 2 innate lymphocytes (ILC2, 15] and induction of Th2-dominant immune response disorder." (PMID 35281428, 2022). "In an animal model of asthma there is increased IL-19 expression and transfer of the IL-19 gene into healthy mice up-regulated IL-4 and IL-5, but not IL-13, however, IL-19 up-regulated IL-13 in “asthmatic” mice." (PMID 18315837, 2008).
breast carcinoma (15 papers, 2012 to 2025). "IL-19 has been implicated in promoting breast cancer cell proliferation; however, its influence on glioblastoma cell proliferation remains ambiguous." (PMID 40057744, 2025). "IL20RA, showing a higher association with IL-19 revealed a significant outcome on the OS of breast cancer patients." (PMID 37675062, 2023). "Being implicated in breast pathogenesis, IL-19 has an autocrine effect in mammary gland cells and represents a major prognostic factor for different types of tumors, including breast cancer." (PMID 30648081, 2018). "IL-19 also promoted proliferation and migration of breast cancer cells, and high IL-19 expression was associated with poor outcomes in breast cancer patients." (PMID 22844641, 2012). "In addition, IL-19 is highly expressed in breast cancer and is associated with a poor clinical outcome." (PMID 36006737, 2022). "IL-19 promotes proliferation and migration directly while secondarily, it provides a microenvironment for tumor development, with high IL-19 expression levels being associated with a poor clinical outcome for breast cancer patients." (PMID 30648081, 2018). "IL-19 expression is positively correlated with tumor metastasis and clinical outcomes in patients with breast cancer and esophageal squamous cell carcinoma." (PMID 40057744, 2025). "Promoting tumor growth, migration, and M2 macrophage polarization, IL-19 has been shown to contribute to an immunosuppressive microenvironment in breast cancer and is a member of the IL-10 cytokine family." (PMID 41348904, 2025). "The IL-19 protein stimulates fibronectin (FN) expression and assembly, metastasis, and cell division in breast cancer (BC) cells." (PMID 37675062, 2023). "High IL-19 expression helps in tumor development, proliferation, metastasis, and migration in breast cancer (BC), suggesting IL-19 as a prognostic marker/indicator." (PMID 37675062, 2023). "For example, TIMER 2.0 and GEPIA were utilized to evaluate the expression profile of IL-19 in several types of cancers and the results revealed that IL-19 is highly upregulated in several cancers including breast cancer." (PMID 37675062, 2023). "IL-19, which is connected to breast pathogenesis and has an autocrine action in BC cells, is a key predictor of prognosis for many tumour forms, including breast cancer." (PMID 37675062, 2023). "Our results indicated that high levels of IL-19 and TNF-α, linked to clinical disease stage and lymph node metastasis, have an autocrine effect on breast cancer cells and produce a milieu conducive to tumour growth." (PMID 35928364, 2022). "This study investigated the alteration of tumour necrosis factor (TNF-α) and interleukin-19 (IL-19) at different clinical disease stages, lymph node metastasis, and ductal carcinoma in women with breast cancer." (PMID 35928364, 2022). "Thirdly, IL-19 is an indicator for breast cancer as it helps to provide the required micro-environment for the progression of tumours." (PMID 35928364, 2022). "In this context, the current study investigates the alteration of TNF-α and IL-19 at different clinical disease stages, lymph node metastasis, and ductal carcinoma in women with breast cancer." (PMID 35928364, 2022). "IL-19 is involved in inflammatory diseases such as rheumatoid arthritis, kidney injury, psoriasis, and breast cancer, and induces angiogenesis in endothelial cells." (PMID 31114590, 2019). "The IL-19 protein induces the assembly and expression of fibronectin (FN), cell multiplication, and metastasis in breast cancer cells." (PMID 30648081, 2018). "IL-19 is reported to directly affect breast cancer cell proliferation, migration, and tumor progression by inducing the expression of cytokines and chemokines while the expression levels are connected to advanced stages, higher mitotic rates, and metastasis." (PMID 30648081, 2018).